HOXB8 (homeobox B8)
Description:
Sequence-specific transcription factor which is part of a developmental regulatory system that provides cells with specific positional identities on the anterior-posterior axis.
Synonyms: HOX2D; HOX2; Hox-2.4
Tractability: No criterion of Open Targets' tractability assessment is met for any kind of drug.
Gene: Protein-coding gene on chromosome 17 (48,611,377 to 48,618,003, reverse strand). Ensembl gene ENSG00000120068.
Subcellular location: Nucleus
Subcellular location (Human Protein Atlas): Nucleoplasm
Gene Ontology:
Molecular function: sequence-specific double-stranded DNA binding; DNA-binding transcription factor activity, RNA polymerase II-specific; RNA polymerase II transcription regulatory region sequence-specific DNA binding; DNA binding; DNA-binding transcription factor activity; DNA-binding transcription repressor activity, RNA polymerase II-specific; sequence-specific DNA binding
Biological process: negative regulation of myeloid cell differentiation; regulation of transcription by RNA polymerase II; negative regulation of transcription by RNA polymerase II; regulation of DNA-templated transcription
Cellular component: nucleoplasm; chromatin; nucleus
Genetic constraint (gnomAD): Loss-of-function variants: 20 observed, 24.81 expected, observed/expected ratio (o/e) 0.81, 90% interval 0.57 to 1.17. The upper end of that interval is the gene's LOEUF score, 1.17, which puts it in group 5 of 6, group 1 being the genes least tolerant of losing a copy. Missense variants: 287 observed, 332.26 expected, observed/expected ratio (o/e) 0.86, 90% interval 0.78 to 0.95. Synonymous variants: 156 observed, 149.98 expected, observed/expected ratio (o/e) 1.04, 90% interval 0.91 to 1.19.
Homologues: Orthologues: chimpanzee HOXB8 (100% identical), dog HOXB8 (100% identical), pig HOXB8 (100% identical), macaque HOXB8 (99% identical), mouse Hoxb8 (98% identical), tropical clawed frog hoxb8 (86% identical), zebrafish hoxb8a (79% identical), rat Hoxb8 (65% identical), zebrafish hoxb8b (65% identical), rabbit HOXB8 (54% identical). Paralogues in human: HOXD8 (61% identical), HOXC8 (61% identical), HOXB7 (34% identical), HOXB6 (34% identical), HOXA5 (33% identical), HOXA6 (33% identical), HOXA7 (33% identical), HOXB5 (33% identical), HOXC6 (32% identical), HOXA4 (30% identical), HOXD4 (30% identical), HOXB4 (28% identical), and 30 more.
Diseases named in the same sentence as HOXB8 in open-access papers:
HOXB8 is named in the same sentence as 56 diseases in open-access papers, as found by Europe PMC text mining. Sharing a sentence is not in itself a finding about the gene and the disease. The quoted sentences say what the papers report.
colorectal cancer (20 papers, 2009 to 2025). A primary or metastatic malignant neoplasm that affects the colon or rectum. "HOXB8 located on chromosome 17 is a known oncogene that is associated with colorectal cancer." (PMID 35629083, 2022). "LINC03057, also known as lnc-HOXB8-1:2 (ENSG00000272763), is an oncogenic lncRNA associated with colorectal cancer progression." (PMID 40863726, 2025). "By literature review, there were no reports on the functional role and molecular mechanism of lnc-HOXB8-1:2 in colorectal cancer." (PMID 36030223, 2022). "The HOXB8 gene is required to maintain the malignant features of colorectal cancer cells, including invasion and migration in vitro and tumor formation and metastasis in a mouse xenograft model." (PMID 34339740, 2021). "Genes upregulated in KRAS‐mt tumors included HOXB6 and HOXB8, two homeobox genes that have been previously reported to be dysregulated in colorectal cancer." (PMID 33817986, 2021). "On the contrary, HOXB8 has been found to promote tumor progression in many malignancies, including gastric cancer, colorectal cancer, ovarian serous carcinoma, and osteosarcoma." (PMID 31978895, 2020). "HOXB8 was also reported to be an oncogene in gastric cancer and colorectal cancer by promoting tumor proliferation and EMT." (PMID 33318296, 2020). "Furthermore, MAFG-DT upregulated HOXB8 via sponging miR-149-3p to promote colorectal cancer progression." (PMID 39735608, 2024). "BACH1 collaborates with HOXB8 in metastasis of colorectal cancer." (PMID 34339740, 2021). "Similarly, HOXB8 acts as an oncogene in several cancers including colorectal cancer, but is a favorable prognostic marker in renal cancer (Human Protein Atlas)." (PMID 34445617, 2021). "Furthermore, upregulated expression of HOXB8 was observed in all stages of colorectal cancer." (PMID 35769986, 2022). "HOXB8 interacts with BACH1 and activates BACH1 itself as well as its target genes transcription in colorectal cancer." (PMID 35154476, 2022). "In colorectal cancer, miR-196a inhibited the expression of HOXA7, HOXB8, HOXC8 and HOXD8 genes, leading to AKT pathway activation and increased cell motility." (PMID 29259267, 2017). "Absence of HOXB8 inhibits the development of colorectal cancer by inactivating Wnt/β-Catenin signaling pathway." (PMID 31827394, 2019). "For example, miR-196a has been studied for its oncogenic roles in glioblastoma, pancreatic adenocarcinoma, breast cancer, oesophageal adenocarcinoma, and colorectal cancer, and shown to target HOX family genes (HOXA7, HoxB7, HOXC8, HOXB8, HOXD8), ERG, HMGA2, ANXA1, S100A9, SPRR2C, KRTS." (PMID 24621885, 2014). "Additionally, in colorectal cancer (CRC), miR-196 could lead to metastasis by inhibiting HoxB8, and it can also decrease the sensitivity of cancer cells to chemotherapy with FOLFOX4, resulting in unfavorable prognosis, supporting it is a favorable prognostic biomarker." (PMID 33289788, 2021).
Anxiety (8 papers, 2020 to 2025). Intense feelings of nervousness, tension, or panic often arise in response to interpersonal stresses. "It remains possible that Hoxb8 mutations are rare in humans or that other disease phenotypes caused by loss of Hoxb8 function obscure anxiety-related symptoms." (PMID 40689083, 2025). "A more detailed phenotypic description of mice with deficient Hoxb8 confirmed that it is one of the most robust models for anxiety-symptoms." (PMID 40689083, 2025). "The inactivation or mutation of the Hoxb8 gene leads to persistent anxiety, OCD-like behaviors, and prolonged self-grooming in mice, resulting in extensive hair loss and severe skin damage." (PMID 39851412, 2025). "Dysfunctional Hoxb8 microglia cause the acquisition of chronic anxiety and an obsessive-compulsive spectrum-like behavior, trichotillomania, in mice." (PMID 35452096, 2022). "Blocking estrogens with trilostane or ovariectomy could block coat loss, overgrooming, anxiety-like behaviors and enhanced stress response in Hoxb8 KO female animals, whereas the administration of 17β-estradiol and progesterone in Hoxb8 KO male animals replicated the anxiogenic phenotype." (PMID 33041996, 2020). "Hoxb8 dysfunction produces over-grooming in both genders but marked anxiety-like responses only in females." (PMID 40689083, 2025). "Nagarajan and colleagues revealed that optogenetic stimulation of Hoxb8 microglia in specific brain regions can trigger anxiety-like and self-grooming behaviors." (PMID 39851412, 2025). "During pre- and post-laser stimulation periods, the mice explored the open and closed arm equally, implying that the higher levels of anxiety are dependent on optogenetic stimulation of Hoxb8 microglia." (PMID 37037872, 2024). "These unanticipated results of optogenetic activation of both microglia populations in the appropriate regions of the brain have completely revised how we view the role of Hoxb8 and non-Hoxb8 microglia in modulating the levels of grooming and anxiety in mice." (PMID 37037872, 2024). "To summarize, herein we demonstrate that two well defined behaviors in mice, anxiety and grooming, can be specifically induced by optogenetic stimulation of Hoxb8 microglia in specific regions of the brain." (PMID 37037872, 2024). "Further, in the home cage we reported the induction of both grooming and anxiety by optogenetic stimulation of only Hoxb8 microglia in the vCA1." (PMID 37037872, 2024). "Herein, we will show that optogenetic activation of Hoxb8 microglia in the same defined regions of the brain induce anxiety, grooming or both." (PMID 37037872, 2024). "Herein we show, that optogenetic stimulation of Hoxb8 microglia in specific regions of the brain induces elevated anxiety, grooming or both." (PMID 37037872, 2024). "We have demonstrated that optogenetic activation of Hoxb8 microglia in specific regions of the brain induces higher levels of anxiety, grooming or both." (PMID 37037872, 2024). "In the home cage, we observed strong induction of both grooming and anxiety in response to optogenetic stimulation of Hoxb8 microglia in the vCA1." (PMID 37037872, 2024). "For example, Hoxb8 microglia function to down regulate anxiety and grooming (i.e., function as brakes), whereas non-Hoxb8 microglia function to upregulate anxiety and grooming (i.e., function as an accelerator)." (PMID 37037872, 2024). "Further, the model is consistent with the genetic disruption of Hoxb8 resulting in chronic anxiety and pathological overgrooming in mice." (PMID 37037872, 2024). "The elevated plus maze test also detected increased freezing time in Hoxb8IRESCre/Ai32 mice compared to C57Bl/6 mice These data support the conclusion that optogenetic activation of Hoxb8 microglia in the vCA1 induces a robust anxiety response." (PMID 37037872, 2024). "Remarkably, not only anxiety but also grooming as well as freezing was induced by optogenetic stimulation of Hoxb8 microglia in the vCA1." (PMID 37037872, 2024).
Anxiety (continued). "Conversely, Hoxb8 mutant males supplemented by progesterone and β-estradiol show increased female levels of pathological grooming and anxiety." (PMID 37037872, 2024). "What is apparent is that the vCA1 hippocampus is very sensitive to optogenetic stimulation of Hoxb8 microglia with respect to both the induction of anxiety and grooming, with the added propensity for freezing, a further reflection of anxiety." (PMID 37037872, 2024). "Targeted deletion of Hoxb8-lineage microglia led to significant grooming and anxiety-like behaviors and stress-response among female rodents, which were ameliorated by suppressing female sex hormones." (PMID 33659962, 2020). "They normally suppress anxiety and Hoxb8 enables this specific cell function." (PMID 40689083, 2025). "Would optogenetic stimulation of Hoxb8 microglia within the vCA1 induce anxiety?" (PMID 37037872, 2024). "We have generated a mouse line in which the disruption of a single gene, Hoxb8, results in both chronic anxiety and OCSD-like behavior, pathological overgrooming, to the point of lesion at the sites of overgrooming (trichotillomania-like behavior, a subset of OCSD)." (PMID 37037872, 2024). "The more excessive grooming and elevated anxiety observed in female Hoxb8 mutant mice can be reduced to male levels by the elimination of female sex hormone production either by removal of the ovaries or by treatment with trilostane which inhibits female sex hormone synthesis." (PMID 37037872, 2024). "Optogenetic stimulation of Hoxb8 microglia within the dorsomedial striatum (DMS) or the medial prefrontal cortex (mPFC) induces grooming, whereas stimulation of Hoxb8 microglia in the basolateral amygdala (BLA) or central amygdala (CeA) produces elevated anxiety." (PMID 37037872, 2024). "In retrospect, we should have suspected that Hoxb8 and non-Hoxb8 microglia work in opposition to each other earlier, based on the severity of the behavioral phenotype resulting from disruption of the Hoxb8 gene in mice, chronic anxiety and pathological overgrooming." (PMID 37037872, 2024). "However, if the normal role of Hoxb8 microglia is to inhibit (down regulate) anxiety and grooming behavior, and optogenetic activation of Hoxb8 microglia release them from this inhibitory role, then the paradox is resolved." (PMID 37037872, 2024). "Optogenetic stimulation of microglia expressing Hoxb8 in the BLA also results in increased anxiety." (PMID 38468130, 2024). "Readers might view the finding that disruption of Hoxb8 or ablation of the Hoxb8 microglia cell lineage gives rise to pathological levels of anxiety and grooming, whereas optogenetic activation of Hoxb8 microglia results in elevated levels of anxiety and grooming as being paradoxical." (PMID 37037872, 2024). "Optogenetic stimulation of Hoxb8 microglia in the DMS and mPFC induces grooming, whereas optogenetic activation in the BLA and CeA induces anxiety." (PMID 37037872, 2024). "Perhaps the most surprising result is that co-optogenetic activation, using Iba1Cre, of both non-Hoxb8 microglia and Hoxb8 microglia in the DMS, mPFC and vCA1 results in quenching grooming in the former and both grooming and anxiety in the vCA1." (PMID 37037872, 2024). "To further examine the anxiety behavior elicited by optogenetic stimulation of Hoxb8 microglia in the BLA and CeA, we used OFTs to assess levels of anxiety, including freezing behavior." (PMID 37037872, 2024). "Expression of Hoxb8 ceases in-utero but anxiety-like symptoms do not appear until onset of sexual maturity." (PMID 40689083, 2025). "It should be stated, that by optogenetic stimulation of Hoxb8 microglia in specific regions of the brain, we are not inducing pathological levels of grooming and/or anxiety." (PMID 37037872, 2024). "Optogenetic activation of Hoxb8 microglia in specific regions of the brain induces higher levels of anxiety, grooming or both, but not pathological levels of anxiety or grooming." (PMID 37037872, 2024).
Anxiety (continued). "In the DMS and mPFC, we did not observe mice freezing in response to optogenetic stimulation of Hoxb8 microglia, a likely reflection that anxiety-like behavior is not induced by optogenetic activation of Hoxb8 microglia in the DMS and mPFC." (PMID 37037872, 2024). "Remarkably, optogenetic stimulation of Hoxb8 microglia within the basolateral amygdala (BLA) and central amygdala (CeA) did not induce grooming, but instead induced elevated levels of anxiety." (PMID 37037872, 2024).
breast carcinoma (8 papers, 2014 to 2023). "In the setting of breast cancer, lncRNA Migration Inhibitory Factor Antisense RNA 1, overexpressed in breast cancer tissues and cells, has been identified to boost the progression through regulation of HOXB8 by binding to miR-1249-3p." (PMID 33093810, 2020). "Decreased expression of miR-718 contributed to the poor prognosis of HCC patients via the up-regulation of homeobox B8 (HOXB8), and there are similar results for breast cancer patients." (PMID 30897788, 2019). "MIF-AS1 acted as a competing endogenous RNA by activating miR-1249-3p/HOXB8 axis in breast cancer." (PMID 32579540, 2020). "Furthermore, the miR-1249-3p/Homeobox B8 (HOXB8) axis was involved in long non-coding RNA MIF-AS1-mediated breast cancer progression." (PMID 31769433, 2019). "The entire mechanism involving FGF2, PBX1/PBX2, and HOXB7/HOXB8 in breast cancer tumorigenesis is not clear." (PMID 37445737, 2023). "Examples include HOXC6 in gastric cancer, HOXB8 in ovarian cancer, and HOXD3 in breast cancer." (PMID 26867567, 2016).
pancreatic cancer (8 papers, 2014 to 2025). "Loss of HOXB6 and HOXB8 in pancreatic cancer cells inhibited cell proliferation, induced apoptosis and senescence and enhanced gemcitabine sensitivity." (PMID 40619489, 2025). "Additionally, naïve M0 macrophages exposed to HOXB8 deficient PDAC cells were unable to differentiate into tumor-associated macrophages, suggesting that HOXB8 promotes the transition of initial anti-tumor macrophage to a tumor-promoting macrophage phenotype in pancreatic cancer." (PMID 40619489, 2025). "To determine if these observations were functionally relevant in PDAC cells, we knocked down (KD) HOXB6 and/or HOXB8 expression using siRNAs (i.e., siHOXB6, siHOXB8, and siHOXB6B8) in the human pancreatic cancer cell lines PANC-1 and AsPC1." (PMID 40619489, 2025). "In this study, we define the role of homeobox protein B6 (HOXB6) and HOXB8 in controlling pancreatic cancer tumorigenesis and immune response." (PMID 40619489, 2025). "Loss of function experiments in pancreatic cancer cell lines demonstrated that HOXB6 and HOXB8 control cancer cell proliferation, viability, apoptosis, senescence, and sensitivity to gemcitabine." (PMID 40619489, 2025). "LINC01006 is certified to promote pancreatic cancer development through functioning as a ceRNA of miR-2682-5p to enhance HOXB8." (PMID 33088221, 2020). "As with HoxA3, no study has previously investigated the expression and clinical significance of HoxB8 in pancreatic cancer." (PMID 31137902, 2019). "Our findings indicate that HOXB6 and HOXB8 play important roles in regulating cell proliferation, immune response, and treatment resistance to promote pancreatic cancer tumorigenesis and could be useful therapeutic targets." (PMID 40619489, 2025). "However, to establish a critical role for HOXB6 and HOXB8 in pancreatic cancer biology, animal models and primary human PDAC cell culture will be needed to verify our findings in an in vivo setting." (PMID 40619489, 2025). "LINC01006 promotes cell proliferation and metastasis in pancreatic cancer via miR-2682-5p/HOXB8 axis, which may facilitate the treatment for PC." (PMID 31827394, 2019). "Interestingly, the expression of HoxA3 and HoxB8 was continuously upregulated in pancreatic cancer cells with increased metastatic ability, while the expression of HoxA10, HoxA11, and HoxB13 was consistently reduced in these cells." (PMID 31137902, 2019). "We hypothesize that HoxB8 is also a metastasis promoter in pancreatic cancer." (PMID 31137902, 2019). "Most importantly, we show that HOXB6 and HOXB8 KD impaired tumor cell proliferation, differentiation, and maintenance further supporting that HOXB6 and HOXB8 are important regulators of pancreatic cancer stem cells." (PMID 40619489, 2025). "Interestingly, HOXB6 and HOXB8 bind to and activate expression of one another and other HOX genes expressed in pancreatic cancer cells suggesting that a HOX transcriptional network is active in PDAC similarly to what has been described in other solid tumors." (PMID 40619489, 2025). "At the same time, SNHG3/miR-2682-5p/HOXB8 axis, ELK1/lncRNA-SNHG7/miR-2682-5p feedback loop, and LINC01006/miR- 2682-5p/HOXB8 axis can promote the proliferation and migration of oral squamous cell carcinoma, bladder cancer, and pancreatic cancer, respectively." (PMID 35465266, 2022).
gastric cancer (7 papers, 2016 to 2022). A primary or metastatic malignant neoplasm involving the stomach. "HOXB8 has been shown to be associated with the development of various cancers, such as colorectal, hepatocellular and gastric cancers." (PMID 35769986, 2022). "It has been reported that HOXB8 serves as a transcription factor to promote the development of gastric cancer." (PMID 31827394, 2019). "HOXB8 has also been proved to be a transcription factor in gastric cancer." (PMID 31827394, 2019).